RUNX3 (RUNX family transcription factor 3)
Diseases named in the same sentence as RUNX3 in open-access papers (continued):
Sharing a sentence is not in itself a finding about the gene and the disease.
keloid (3 papers, 2007 to 2025). An irregularly shaped, elevated mark on the skin caused by deposits of excessive amounts of collagen during wound healing. "The expression levels of SIRT1, EZH2 and RUNX3 in keloid specimens and their normal adjacent tissues were detected by Western blot." (PMID 36476345, 2022). "The results showed that the expression levels of SIRT1 (P < 0.05) and RUNX3 (P < 0.05) in keloid tissues were significantly lower than those in normal adjacent skin tissues." (PMID 36476345, 2022). "Herein, we investigated the mechanism of abnormal proliferation in keloids involving Sirtuin 1(SIRT1)/ Zeste Homolog 2 (EZH2)/ Runt-related transcription factor 3 (RUNX3)." (PMID 36476345, 2022). "In this study, we first found that in keloid tissues, the expression level of RUNX3 was significantly lower than that in normal tissues." (PMID 36476345, 2022). "Herein, we aim to investigate the role and mechanism of SIRT1/EZH2/RUNX3 in abnormal proliferation of benign keloids." (PMID 36476345, 2022). "Cell proliferation was detected with CFSE after overexpression of RUNX3, which showed that RUNX3 overexpression significantly inhibited cell proliferation of keloid fibroblasts." (PMID 36476345, 2022). "Similar results of SIRT1, EZH2 and RUNX3 were also observed in keloid fibroblasts and normal fibroblasts." (PMID 36476345, 2022). "Additionally, we identified the pivotal regulators of each specific sub-fibroblast cluster, including IRF4 for scar-related, CLOCK for keloid-related, RUNX3 for scleroderma-related, and HOXC4 for normal skin sub-fibroblast clusters." (PMID 41350567, 2025). "Notably, pivotal regulators for each sub-fibroblast cluster were discovered: IRF4 for scar, CLOCK for keloid, RUNX3 for scleroderma, and HOXC4 for normal skin." (PMID 41350567, 2025). "Study has shown that Pa-PDT may be a potential treatment modality for keloids, while RUNX3 may improve the sensitivity to PaPDT in keloid fibroblast KFs and thus the effect on the scar airway." (PMID 36476345, 2022). "The mechanism of cell proliferation involving SIRT1/EZH2/RUNX3 in benign keloids is still unclear." (PMID 36476345, 2022). "In summary, our study shows that SIRT1 could promote proliferation by reducing RUNX3 expression in keloids through deacetylation of EZH2." (PMID 36476345, 2022). "Conclusively, the SIRT1/EZH2/RUNX3 axis may be an important pathway in the regulation of abnormal proliferation in keloids." (PMID 36476345, 2022). "In this study, we found that the overexpression of RUNX3 in keloid fibroblasts helped to inhibit cell proliferation, and the detection of cell cycle and cell cycle-related proteins revealed that the effect of RUNX3 on cell proliferation may be related to its regulation on cell cycle." (PMID 36476345, 2022). "SIRT1/EZH2/RUNX3 axis may be important for regulating abnormal proliferation in keloids." (PMID 36476345, 2022). "Considering that RUNX3 may act at tumor suppressor gene in keloids, we analyzed the correlation of SIRT1, EZH2, and RUNX3 expression in keloid tissues and found that there were negative regulatory relationships between SIRT1 and EZH2, and between EZH2 and RUNX3." (PMID 36476345, 2022).
metastatic cancer (3 papers, 2018 to 2023). A carcinoma which has spread from the original site of growth to another anatomic site. "Conversely, the aberrant upregulation of RUNX3 in metastatic cancer may be targeted therapeutically by small molecule inhibitors, such as the pyrrole-imidazole polyamide Chb-M’, benzodiazepine Ro5-3335, as well as 2-pyridyl benzimidazole AI-4-57 and derivatives." (PMID 36766749, 2023). "As both RUNX3 and TGF-β play a tumor suppressor role in cancer development, their elevated CpG methylations inhibited their expression in metastatic cancer model thereby contributing to higher degree of malignancy." (PMID 29651226, 2018).
Obesity (3 papers, 2023 to 2025). Accumulation of substantial excess body fat. "rs548267220 has not appeared in the GWAS catalog previously (5th Nov 2024), though there are 142 entries for RUNX3 including haematological traits, kidney function, allergic diseases, blood pressure, and obesity." (PMID 40696379, 2025). "DEGs in the CDs significantly affected biologically related functions and signaling pathways such as IL-4 Signaling Pathway, RUNX3 Regulates Notch Signaling, IL-1 and Megakaryocytes in Obesity Pathway, and Overview of Leukocyteintrinsic Hippo Pathway." (PMID 37274215, 2023). "Functional analysis revealed that six MRHGs significantly affected biologically relevant functions and signaling pathways such as IL-4 Signaling Pathway, RUNX3 Regulates Notch Signaling Pathway, IL-1 and Megakaryocytes in Obesity Pathway, and Overview of Leukocyteintrinsic Hippo Pathway." (PMID 37274215, 2023). "In our study, the MQ group exhibited restored expression of HFD‐dysregulated genes (Runx3 and parvalbumin) while concurrently counteracting HFD‐induced obesity." (PMID 41306337, 2025).
osteosarcoma (3 papers, 2019 to 2026). A usually aggressive malignant bone-forming mesenchymal neoplasm, predominantly affecting adolescents and young adults. "However, RUNX3 expression in ES was significantly higher when compared with the expression in osteosarcoma." (PMID 33924679, 2021).
renal fibrosis (3 papers, 2018 to 2024). A final common manifestation of a wide variety of chronic kidney diseases characterized by glomerulosclerosis and tubulointerstitial fibrosis. "RUNX3 is a transcription factor that works in balance with the STAT5 transcription factor in the renal fibrosis pathway, suggesting that altered methylation and thus expression of RUNX3 may lead to aberrant renal fibrosis, a hallmark of CKD." (PMID 30359254, 2018). "Apelin inhibits the expression of TGF-β/smad, and TGF-β/smad may regulate RUNX3 to enter the nucleus, thereby implementing the negative feedback regulation of Apelin against renal fibrosis." (PMID 39014438, 2024). "In the current study, we have demonstrated that expression of RUNX1, but not RUNX2 or RUNX3, was induced in the process of TGF-β-induced EMT in a SMAD3-dependent manner and in UUO-induced renal fibrosis in vivo." (PMID 29759484, 2018).
acute lymphoblastic leukemia (2 papers, 2022 to 2024). Leukemia with an acute onset, characterized by the presence of lymphoblasts in the bone marrow and the peripheral blood. "However, the reduced RUNX3 levels correlated with Ph chromosome occurrence in adult acute lymphoblastic leukemia cases (p = 0.023)." (PMID 36005134, 2022).
acute myocardial infarction (2 papers, 2021 to 2022). Necrosis of the myocardium, as a result of interruption of the blood supply to the area. "In cardiac, Kcnq1ot1 recruits DNA methyltransferase 1 (DNMT1) to the RUNX3 promoter region and inhibit Runx3 expression, regulating the proliferation and apoptosis of CMEC and induces inflammatory response during myocardial infarction." (PMID 34604208, 2021).
Ad (2 papers, 2018 to 2023). "Conceivably, lung AD cells that develop as a result of Runx3 inactivation are unable to defend against oncogenic K-Ras, resulting in the transition from AD to ADC upon oncogenic K-Ras mutation." (PMID 37887282, 2023). "Genotyping of the lung tumors confirmed K-Ras activation, Runx3 inactivation by Ad-Cre infection, and Runx3 restoration via tamoxifen treatment." (PMID 37887282, 2023). "Therefore, the rare Tomato-positive cells detected in the lungs of KRL/F-TAM(+)-4w and KRL/F-TAM(+)-10w mice suggest that nearly all the K-Ras-activated lung AD cells and ADC cells were eliminated through Runx3 restoration." (PMID 37887282, 2023).
astrocytoma (2 papers, 2019 to 2023). "In present study we found tight RUNX3 association with astrocytoma tumour grade as well as patient age and survival." (PMID 31467531, 2019). "RUNX3 promoter methylation analysis showed gradually increasing RUNX3 methylation frequency along astrocytoma grade." (PMID 31467531, 2019). "Weighty lower RUNX3 protein level was observed in GMB specimens compared to grade II-III astrocytomas." (PMID 31467531, 2019). "All astrocytoma patients were stratified (n=136) in two groups: having tumours with methylated RUNX3 gene promoter and with unmethylated promoter." (PMID 31467531, 2019). "Functional assessment revealed putative-oncosupressive acting of RUNX3 in astrocytomas since gene is methylated and silenced in GBM cell lines and restoration of RUNX3 expression weighty reduced tumour cell viability." (PMID 31467531, 2019). "Functional assessment revealed putative-oncosupressive acting of RUNX3 in astrocytomas what is in the line with expression data from astrocytoma specimen's analysis." (PMID 31467531, 2019). "Significant impact of RUNX3 on patient survival as well as other clinicopathological features indicates gene as potential prognostic marker in astrocytomas." (PMID 31467531, 2019). "Of these subtypes, RUNX1, RUNX2, and RUNX3 in astrocytoma is higher than that oligodendroglioma." (PMID 36321611, 2023).
atherosclerosis (2 papers, 2016 to 2025). A disease characterized by the build-up of fatty material and calcium deposition in the arterial wall resulting in partial or complete occlusion of the arterial lumen. "The results indicated Hnf4a, Ppara, Vdr, and Runx3 as the TFs most likely to regulate the production of these lncRNAs, and might play roles in inflammatory and metabolic processes in atherosclerosis." (PMID 27698357, 2016). "Interestingly, several of these transcription factors, including RUNX3, STAT1, IRF7, and the Th2 hallmark GATA3, had already been implicated in lesion formation in experimental models of atherosclerosis." (PMID 41039608, 2025). "Since RUNX3 is reported to exert much of its T cell regulatory function through PRDM1, we focused on the role of T cell PRDM1 in atherosclerosis." (PMID 41039608, 2025).
atrophic gastritis (2 papers, 2020 to 2023). "An increase in methylated RUNX3 copy numbers was significantly related to tumor size, massive submucosal invasion (sm2), and lymph-vascular invasion, but not to the H. pylori status and the severity of endoscopic gastric atrophy." (PMID 32224873, 2020).
bladder tumor (2 papers, 2009 to 2015). "Overexpression of RUNX3 has previously been associated with functional mutations or protein mislocalization in breast, gastric and bladder tumors." (PMID 19521519, 2009).
bladder urothelial carcinoma (2 papers, 2015 to 2023). "This analysis revealed that CNAs negatively correlated with RUNX3 expression most significantly in bladder urothelial carcinoma (BLCA) (n = 404, p = 9.28 × 10−6) and lung adenocarcinomas (LUAD) (n = 513, p = 8.78 × 10−7)." (PMID 37190015, 2023).
brain tumor (2 papers, 2019 to 2020). "Mei and colleagues showed that RUNX3 protein expression is decreased in benign and malignant brain tumours as compared to normal or adjacent tissue." (PMID 31467531, 2019). "The results of the MS‐HRM analysis of all analyzed genes (SFRP1, SFRP2, RUNX3, CBLN4, INA, MGMT, and RASSF1A) showed that their promoter sequence methylation level is significantly higher (P < 0.0001) in DNA samples from brain tumor patients than in the non‐neoplastic brain sample." (PMID 32783304, 2020).
breast invasive ductal carcinoma (2 papers, 2017 to 2021). "For RUNX3, alterations were mainly found to be amplified in breast invasive ductal carcinoma (0.13%)." (PMID 34485309, 2021). "RUNX3 hypermethylation was significantly correlated with the risk of ductal carcinoma in situ (DCIS) and invasive ductal carcinoma (IDC), OR was 50.37, p < 0.00001 and 22.66, p < 0.00001 respectively." (PMID 27825140, 2017). "The subtypes with the highest frequency of all alternate types were breast invasive lobular carcinoma, breast invasive carcinoma NOS, and breast invasive ductal carcinoma for RUNX1, RUNX2, and RUNX3, respectively." (PMID 34485309, 2021).
childhood asthma (2 papers, 2020 to 2021). "TLE1 was found to be in the susceptibility locus for childhood asthma as it interacts with RUNX3 to inhibit dendritic cell maturation." (PMID 33791298, 2021).
chondrosarcoma (2 papers, 2019 to 2023). A malignant cartilaginous matrix-producing mesenchymal neoplasm arising from the bone and soft tissue. "Homozygous deletion of Runx3 exhibited growth suppression of wild-type mesenchymal chondrosarcoma cells but not Runx2-knockout cells in vitro, whereas growth property of sarcoma in vivo was not affected significantly by Runx3 knockout both in wild-type and Runx2-knockout sarcoma cells." (PMID 37212282, 2023).
colorectal tumors (2 papers, 2013 to 2019). "Finally, we performed methylation-specific PCR on 76 colorectal tumors to determine DNA methylation status for CSMD1 and known methylation targets ALX4, RUNX3, NEUROG1, and CDKN2A." (PMID 23505554, 2013).
cutaneous melanoma (2 papers, 2015 to 2016). A primary melanoma arising from atypical melanocytes in the skin. "The study found miR‐532‐5p was overexpressed in cutaneous melanoma and anti‐miR‐532‐5p inhibited RUNX3 mRNA and protein expression." (PMID 26515139, 2016). "Although inhibition of miR‐532‐5p increased RUNX3 expression in cutaneous melanoma 16, there was still no direct evidence that RUNX3 was a direct target of miR‐532‐5p, as well as the regulation of RUNX3 by miR‐532‐5p in GC." (PMID 26515139, 2016).
cutaneous T-cell lymphoma (2 papers, 2019 to 2024). "Interestingly, RUNX2 is connected to the RUNX3 gene which is already known to be dysregulated in cutaneous T-cell lymphoma, emphasizing the necessity of looking further into this gene as a potential biomarker." (PMID 39435287, 2024).
diabetic kidney disease (2 papers, 2022 to 2024). Progressive kidney disorder caused by vascular damage to the glomerular capillaries, in patients with diabetes mellitus. "Nonetheless, clinical investigations are warranted to explore the therapeutic potential of targeting Apelin and RUNX3 for diabetic nephropathy." (PMID 39014438, 2024). "RUNX3 activated Apelin and regulated the SIRT1/FOXO signaling pathway, resulting in the suppressed cell proliferation and fibrosis in diabetic nephropathy." (PMID 39014438, 2024).
endometrial cancer (2 papers, 2014 to 2023). Primary or metastatic malignant neoplasm involving the endometrium (mucous membrane that lines the endometrial cavity). "We also found that two genes, RASSF2 and RUNX3, were reported to be associated with endometrial carcinoma." (PMID 25298284, 2014).
esophageal tumors (2 papers, 2014 to 2020). "Studies have shown low level of RUNX3 expression in esophageal tumor samples and its expression has been associated with radio-resistance and poor prognosis." (PMID 32943993, 2020). "It was reported that the loss of RUNX3 mRNA expression was statistically correlated with the promoter hypermethylation in esophageal tumors (P<0.001)." (PMID 25229459, 2014). "Here, we investigated the status of RUNX3 in esophageal tumors from North Indian patients." (PMID 32943993, 2020). "Here, we studied the expression of RUNX3 and EZH2 in 58 esophageal tumors along with paired adjacent normal tissue." (PMID 32943993, 2020).
injury (2 papers, 2019 to 2022). Damage inflicted on the body as the direct or indirect result of an external force, with or without disruption of structural continuity. "Similarly, we also found that, compared to sham rats, IL-1β, CXCL1, CXCL11, CCL2, and transcription factor (Spil/Pu.1, Runx3, and IκBz) are obviously elevated at 7 days following nerve injury." (PMID 31708740, 2019).
kidney cancer (2 papers, 2021 to 2022). Primary or metastatic malignant neoplasm involving the kidney. "Overall, the obtainedresults indicated significantly elevated expression of RUNX1 (with fold changes of 6.58 to 6.51) and RUNX3 (with fold changes of 2.7 to 8.32) in kidney cancer." (PMID 34294773, 2021). "Furthermore, the relationship between expressions of RUNX1, RUNX2and RUNX3 and prognosis of KIRC were performed by GEPIA and the results revealed that higher expression of RUNX1 had poorer overall survive (OS) in kidney cancer patients (p < 0.001)." (PMID 34294773, 2021).
leiomyoma (2 papers, 2007). A well-circumscribed benign smooth muscle neoplasm characterized by the presence of spindle cells with cigar-shaped nuclei, interlacing fascicles, and a whorled pattern. "They included several genes such as NR2F1, PNN, Smad4, Smad5, STAT5B, JUN, TGIF2, and ATF1 that were over-expressed while RUNX3, STAT1, STAT6, EGR3, GAS7, Smad1, and EDF1 were underexpressed in leiomyomas as compared to keloid/incisional scars." (PMID 17718906, 2007). "In contrast, the expression of EGR3, ECM2, THBS1, GAS1 and FBLN5 in scars and RUNX3 and COL18 expression in peritoneal adhesions was higher as compared to leiomyomas." (PMID 17718906, 2007).
malaria (2 papers, 2019 to 2023). Malaria is a serious and sometimes fatal disease caused by a parasite that commonly infects a certain type of mosquito which feeds on humans. "Level of RUNX3 was also found decreased in all the malaria sub-groups with a significantly decreased status among UC2 groups compared to both the control subjects." (PMID 31614626, 2019). "More than 95% of the expanded clones sharing identical TCR clonotypes in protected participants during a malaria illness, expressed a robust TH1 cytolytic effector program including transcripts encoding for multiple lytic effector proteins and the TFs ZEB2, T-BET, and RUNX3 (cluster 1)." (PMID 38001069, 2023).
myeloid leukemia (2 papers, 2023 to 2024). A clonal proliferation of myeloid cells and their precursors in the bone marrow, peripheral blood, and spleen. "Contrarily, sustained EVL and RUNX3 overexpression was associated with lymphoid and myeloid leukemia occurrence, respectively." (PMID 37371794, 2023).
myeloproliferative disease (2 papers, 2022 to 2023). "Loss of RUNX3 was shown to cause a mild expansion of HSC and myeloid cells in aged mice, whereas disruption of both RUNX1 and RUNX3 in mice led to BM failure and myeloproliferative disease characterized by DNA repair defects." (PMID 35490198, 2022). "Double knockout (DKO) mice of Runx1 and Runx3 showed co-occurrence of bone marrow failure (BMF) and myeloproliferative disorder (MPD)." (PMID 36672189, 2023).
osteoporosis (2 papers, 2020 to 2021). A condition of reduced bone mass, with decreased cortical thickness and a decrease in the number and size of the trabeculae of cancellous bone (but normal chemical composition), resulting in increased fracture incidence. "Since SATB2, ATF4 and Runx3 are three key mediators of osteoporosis, western blot analysis was used to detect the expression levels of their proteins." (PMID 34043680, 2021). "We identified two ceRNA regulatory pathways in this osteoporosis mouse model—novel circRNA 0020/miR-206-3p/Nnmt and circRNA 3832/miR-3473e/Runx3, which were validated by real-time PCR." (PMID 32616775, 2020). "Therefore, it can be suggested that Runx3 plays a crucial role in osteoporosis." (PMID 34043680, 2021). "Collectively, these studies demonstrated that, SATB3, Runx3 and ATF4 participated in the progression of osteoporosis." (PMID 34043680, 2021).
ovarian endometriosis (2 papers, 2018 to 2024). A non-neoplastic disorder characterized by the growth of endometrial tissue in the ovaries. "Further, estrogen influences epigenetic processes by regulating the DNA methyltransferase 1 (DNMT1)-dependent hypermethylation of the runt-related transcription factor 3 (RUNX3) in the malignant transformation of ovarian endometriosis." (PMID 38673891, 2024).
prostate adenocarcinoma (2 papers, 2016 to 2023). "RUNX1, RUNX2, and RUNX3 were all highly correlated with immune cell infiltration in the HNSC, KIRC, LGG, liver hepatocellular carcinoma (LIHC), and prostate adenocarcinoma (PRAD)." (PMID 36321611, 2023).